IGFBP4 (insulin like growth factor binding protein 4)
Description:
IGF-binding proteins prolong the half-life of the IGFs and have been shown to either inhibit or stimulate the growth promoting effects of the IGFs on cell culture. They alter the interaction of IGFs with their cell surface receptors.
Synonyms: IGFBP-4; IBP4; BP-4; HT29-IGFBP
Tractability: Small molecule: it belongs to a druggable protein family. Antibody: its Gene Ontology location is reachable by antibodies, with high confidence; UniProt places it where antibodies can reach, with medium confidence; UniProt predicts a signal peptide or a membrane-spanning region. PROTAC: ubiquitination databases record sites on it; a small molecule that binds it is known.
Target class: Secreted protein
Gene: Protein-coding gene on chromosome 17 (40,443,446 to 40,457,727, forward strand). Ensembl gene ENSG00000141753.
Subcellular location: Secreted
Pathways (Reactome):
Metabolism of proteins: Post-translational protein phosphorylation; Regulation of Insulin-like Growth Factor (IGF) transport and uptake by Insulin-like Growth Factor Binding Proteins (IGFBPs)
Gene Ontology:
Molecular function: protein binding; insulin-like growth factor I binding; insulin-like growth factor II binding; signaling receptor binding; insulin-like growth factor binding
Biological process: negative regulation of canonical Wnt signaling pathway; regulation of insulin-like growth factor receptor signaling pathway; signal transduction
Cellular component: endoplasmic reticulum lumen; extracellular region; non-collagenous component of interstitial matrix
Genetic constraint (gnomAD): Loss-of-function variants: 9 observed, 17.08 expected, observed/expected ratio (o/e) 0.53, 90% interval 0.32 to 0.92. The upper end of that interval is the gene's LOEUF score, 0.92, which puts it in group 3 of 6, group 1 being the genes least tolerant of losing a copy. Missense variants: 307 observed, 287.4 expected, observed/expected ratio (o/e) 1.07, 90% interval 0.97 to 1.17. Synonymous variants: 148 observed, 119.97 expected, observed/expected ratio (o/e) 1.23, 90% interval 1.08 to 1.41.
Homologues: Orthologues: macaque IGFBP4 (100% identical), chimpanzee IGFBP4 (99% identical), dog IGFBP4 (98% identical), pig IGFBP4 (96% identical), rabbit IGFBP4 (95% identical), mouse Igfbp4 (91% identical), rat Igfbp4 (90% identical), tropical clawed frog igfbp4 (57% identical), guinea pig IGFBP4 (52% identical). Paralogues in human: IGFBP2 (40% identical), IGFBP5 (34% identical), IGFBP3 (31% identical), IGFBP1 (29% identical), IGFBP6 (26% identical).
Diseases named in the same sentence as IGFBP4 in open-access papers:
IGFBP4 is named in the same sentence as 130 diseases in open-access papers, as found by Europe PMC text mining. Sharing a sentence is not in itself a finding about the gene and the disease. The quoted sentences say what the papers report.
breast carcinoma (25 papers, 2005 to 2025). "Increased serum IGFBP-4 levels have also been associated with breast cancer, melanoma, and acute lymphoblastic leukemia." (PMID 22264331, 2012). "Intact cell-associated IGFBP4 as well as IGFBP4 cleavage fragments were identified in both normal mammary fat pad tissue (lane 3) and 4T1.2 mammary tumours (lanes 4 and 5)." (PMID 19536088, 2009). "In breast cancer, high IHC staining for IGFBP-4 was associated with longer PFS and OS." (PMID 26217584, 2015). "Notably, blocking IGFBP-4 was also associated with decreased cell motility in breast cancer." (PMID 32792532, 2020). "IGFBP-4 serum levels were found to be higher in breast cancer, epithelial ovarian cancer, and lung cancer." (PMID 41303367, 2025). "Knockdown of MEX3A significantly inhibited breast cancer cell proliferation, migration, and invasion by promoting IGFBP4 expression, revealing the regulatory mechanism of MEX3A targeting IGFBP4 in BC cells." (PMID 37433992, 2023). "Patients with high IGFBP4 mRNA expression levels have better overall survival and disease-free survival rate in breast cancer." (PMID 37088808, 2023). "IGFBP4 has been mainly studied in colon cancer, lung cancer, gastric cancer, ovarian cancer and breast cancer." (PMID 37088808, 2023). "IGFBP4 mRNA expression is an independent prognostic factor in breast cancer patients, and its mRNA expression level is positively correlated with estrogen receptor status." (PMID 35859293, 2022). "In liver and breast cancer, IGFBP4 inhibits growth and invasion, and its overexpression is often associated with a better prognosis." (PMID 34122521, 2021). "Elevated expression of IGFBP4 can lead to positive disease-free survival and OS in breast carcinoma, while IGFBP4 has a tumor-promoting effect on renal cell carcinoma by activating the Wnt/β-catenin signaling pathway." (PMID 33282953, 2020). "We subsequently examined the expression of IGFBP4 in the breast cancer cell lines and found it to be expressed in eight of the twelve cell lines examined." (PMID 32792532, 2020). "We therefore examined the effects of wild-type IGFBP4 and protease-resistant IGFBP4 expression on tumour growth in an orthotopic model of breast cancer." (PMID 19536088, 2009). "We are currently investigating the therapeutic potential of recombinant protease-resistant IGFBP4 in breast cancer." (PMID 19536088, 2009). "We anticipated that wild-type IGFBP4 would be unable to block IGF1 activity in 4T1.2 mammary tumours in vivo because of the presence of active PAPP-A in mammary tissue." (PMID 19536088, 2009). "And, MEX3A promote the malignant progression of breast cancer by directly targeting IGFBP4 mRNA." (PMID 37433992, 2023). "Furthermore, breast cancer patients with high IGFBP4 mRNA expression had better disease-free survival and overall survival rates than patients with low expression." (PMID 35859293, 2022). "In the orthotopic 4T1.2 breast cancer model, we demonstrate that the expression of a protease-resistant IGFBP4, where the PAPP-A cleavage site has been mutated without altering its IGF-binding capacity, inhibited 4T1.2 tumour growth." (PMID 19536088, 2009). "A recent study also revealed that IGFBP4 mRNA expression is an independent prognostic factor in breast cancer, and that patients with ER-positive breast cancer with higher levels of IGFBP4 tumor mRNA expression and lower levels of IGFBP5 mRNA had a better prognosis." (PMID 18928543, 2008). "IGFBP4, an estrogen-regulated gene, is downregulated in tamoxifen-resistant cell lines, forms part of a molecular signature of poor prognosis ER-positive breast cancer, and could help to identify people who may benefit from endocrine therapy in ovarian cancer." (PMID 18928543, 2008). "Studies have also shown that IGFBP4 interferes with the E2-induced activation of the Akt/PKB pathway and prevents fully hormone-dependent activation of ERα and breast cancer cell growth in an IGF- and IGF-IR-independent manner." (PMID 35859293, 2022).
breast carcinoma (continued). "Antibody treatment of the breast cancer cell line MDA-MB-231 with anti-PAPP-A and anti-IGFBP4 antibodies decreased the invasive ability of these cells." (PMID 32792532, 2020). "We interrogated the TCGA provisional dataset for association of gene expression alterations in the IGF signalling components analysed above (IGF-1R, IFG-2R, IGFBP4, IRS-1, IRS-2) with survival in breast cancer." (PMID 32792532, 2020). "The most significant ones include TFF1, CCND1, IGFBP4, C3, ADORA1, GREB1, and MYC, which have been shown by candidate gene analysis to be estrogen regulated genes in breast cancer cell lines." (PMID 21878096, 2011). "The approach described here – PAPP-A-resistant IGFBP4 – will inhibit IGF activity even in the presence of the PAPP-A protease and there is some evidence that PAPP-A plays a role in human breast cancer progression." (PMID 19536088, 2009). "Breast cancer cells typically express several IGFBPs, with IGFBP-2, IGFBP-3, IGFBP-4 and IGFBP-5 being observed most often." (PMID 15642160, 2005). "Several in vitro studies report that sea buckthorn extracts from seeds, berries, leaves, or juice inhibit breast cancer cell proliferation and induce apoptosis via mechanisms such as CASP3, IGFBP4, GADD34 modulation, cell cycle arrest, and TNF–NF‐κB signaling inhibition." (PMID 41409192, 2025). "We reported that PAPP-A or IGFBP4 antibody-mediated neutralisation abrogated migration and invasion but not proliferation in breast cancer cells." (PMID 32792532, 2020). "Furthermore, a high mRNA ratio of IGFBP-5/IGFBP-4 from patients’ tissue enhanced the power of its poor prognostic value, and also predicted resistance to the IGF-1R and INSR TKI, BMS-536924, in a breast cancer cell line." (PMID 26217584, 2015). "The data presented here showing that a protease-resistant IGFBP4 blocks IGF activity and therefore tumour growth and angiogenesis, suggests that protease-resistant IGFBP4 may have value as a novel breast cancer treatment." (PMID 19536088, 2009). "However, the involvement of IGFBP4 in breast cancer progression has not been previously reported." (PMID 37433992, 2023). "However, an opposite pattern was identified for other of them (VEGFR2/KDR, CYR61/CCN1, IGFBP1, IGFBP4, IGFP6) and no changes for CTGF/CCN2, and IGFP6 across the breast cancer subtypes." (PMID 33531624, 2021).
lung carcinoma (20 papers, 2016 to 2025). "IGFBP-4 expression has been shown to be associated with cancer types such as lung cancer, epithelial ovarian cancer, and glioblastomas." (PMID 41303367, 2025). "For instance, changes in IGFBP4 levels have been linked to tumor cell proliferation in lung cancer and have shown associations with prognosis." (PMID 38760675, 2024). "Conversely, IGFBP4 overexpression was found adversely associated with the prognosis of lung cancer patients." (PMID 35688943, 2022). "In the same study, IGFBP-4 knockdown in the lung cancer cell line A549 caused a decrease in the mRNA and protein levels of IGFBP-4." (PMID 34177367, 2021). "The pregnancy-associated plasma protein-A (PAPP-A) has proteolytic activity towards IGFBP-4, and both proteins have been associated with a variety of cancers, including lung cancer." (PMID 34177367, 2021). "These elevated levels suggest that IGFBP-4 is highly associated with lung cancer." (PMID 34177367, 2021). "Previous studies reported that in lung cancer, the promoter region of IGFBP4 is hypermethylated, and the expression of IGFBP4 is negatively correlated with that of Ki-67." (PMID 37349627, 2024). "In lung cancer, IGFBP4 serum protein levels are appreciably elevated in tumor samples, and it is adversely associated with the long-term prognosis of patients." (PMID 37433992, 2023). "A 2021 study of 60 lung cancer patients found higher levels of IGFBP-4 in all stages of disease and histologic subgroups of lung cancer when compared to healthy individuals." (PMID 35198099, 2022). "In our study, the IGFBP-4 levels were measured in the serum of healthy individuals and patients with lung cancer." (PMID 34177367, 2021). "The expression levels of lnc-IGFBP4–1, mRNA levels of IGFBP4 in 159 paired lung cancer samples and adjacent, histological normal tissues by qRT-PCR." (PMID 28946875, 2017). "We also found that the expression of IL-6, CXCL16, or IGFBP-4 significantly predicted the poor overall survival in patients with lung cancer." (PMID 27095254, 2016). "Additionally, for each of the histological subgroups, we also analysed the differences in the IGFBP-4 levels among the patients with different stages of lung cancer, as determined by the TNM staging system." (PMID 34177367, 2021). "Considering all these lung cancer-related studies on IGFBP-4, it may be concluded that IGFBP-4 is involved in the regulation of cancer development in various ways and may also be a potential biomarker." (PMID 34177367, 2021). "Secondly, the IGFBP-4 levels were significantly elevated in untreated lung cancer patients compared to those in the control group, suggesting that IGFBP-4 could be a promising biomarker." (PMID 34177367, 2021). "In the same study, while IGFBP-4 expression was found to be decreased in tissues of lung cancer, the expression levels of lnc-IGFBP-4 were increased compared to those in the control group, and this increase significantly correlated with the disease stage and metastasis status." (PMID 34177367, 2021). "In conclusion, we argue that, compared to PAPP-A, IGFBP-4 may be a promising innovative biomarker for lung cancer." (PMID 34177367, 2021). "Although currently there is no research on the relationship between IGFBP4 and prognosis in liver cancer, it has been reported to be associated with prognosis in various cancer types, like lung cancer." (PMID 34488748, 2021). "Although PAPP-A has been suggested in many studies as a potential biomarker for lung cancer, our results highlighted IGFBP-4 instead, the serum levels of which were found to be significantly different between lung cancer patients and healthy control individuals." (PMID 34177367, 2021). "High expression of IGFBP4 is related to metastasis and worse median survival rate in lung cancer." (PMID 33282953, 2020). "In addition to HCC, IGFBP4 can impair the invasiveness of colorectal cancer and lung cancer cells." (PMID 37349627, 2024).
lung carcinoma (continued). "It has been found that higher amounts of IGFBP4 mRNA in normal lung than in tumor tissues derived from lung cancer patients, and the expression level of IGFBP4 is in association with tumor differentiation, the poorly differentiated adenocarcinoma cells often lost their IGFBP-4 expression." (PMID 28946875, 2017). "At the same time, several genes downregulated in NPRL2−/− cells are also known to be downregulated in lung cancer (FBLN2, LBH, AMPH-1), glioblastoma (ELAVL2), and liver cancer (IGFBP4)." (PMID 41469472, 2025). "In this study, the IGF-1, IGFBP-4, and PAPP-A levels were analysed in samples from patients with different lung cancer types and stages to evaluate their potential use as lung cancer biomarkers." (PMID 34177367, 2021). "However, IGFBP-4 may have better potential than PAPP-A as a lung cancer biomarker." (PMID 34177367, 2021). "Based on this, we aimed to evaluate both IGFBP-4 and PAPP-A as potential lung cancer biomarkers and to investigate the serum levels of these molecules in different histological types of lung cancer." (PMID 34177367, 2021). "Among them, IGFBP2, IGFBP3, IGFBP4, IGFBP6 and IGFBP7 showed higher expression levels, especially in gastric, liver and lung cancer cell lines; conversely, IGFBP1, IGFBP5 and IGFBPL1 showed relatively lower expression, particularly in colorectal, gastric and kidney cancer cell lines." (PMID 37088808, 2023). "IGFBP4 overexpression can inhibit tumor proliferation and induce apoptosis by increasing the expression level of the proapoptotic protein BAX and decreasing that of the antiapoptotic protein BCL2 in A549 lung cancer cells." (PMID 36164607, 2022). "The serum IGFBP-4 levels in all patients with lung cancer, regardless of treatment status and histological differences, were significantly higher than those in the control group (p<0.005)." (PMID 34177367, 2021). "Although the elevated serum levels of PAPP-A have been found in patients with lung cancer, IGFBP-4 has not been adequately evaluated as a biomarker for lung or other types of cancer." (PMID 34177367, 2021). "IGFBP4 is generally considered to have a negative regulatory role on IGF-1, for example, both IGFBP4 and IGFBP2 were found to be down-regulated through promoter hypermethylation in lung carcinomas." (PMID 28443133, 2017). "Thus, we aimed to evaluate the use of IGFBP-4 and PAPP-A as potential biomarkers for lung cancer." (PMID 34177367, 2021). "Further studies in a larger population sample are necessary to confirm the role of IGFBP-4 as a potential biomarker in lung cancer and to determine whether it is clinically useful or not." (PMID 34177367, 2021). "In addition to non-cancerous tissues, IGFBP-4 is known to be expressed in different histological types of lung cancer cells, such as adenocarcinoma and NSCLC." (PMID 34177367, 2021).
ovarian carcinoma (12 papers, 2008 to 2025). A malignant neoplasm originating from the surface ovarian epithelium. "Moreover, elevated expression of IGFBP4 was associated with worse overall survival in ovarian cancer patients who received platin chemotherapeutic regimen." (PMID 36983585, 2023). "Contrary to the hypothesis that those upregulated candidate genes might be a survival benefit for ovarian cancer, high IGFBP4 and TGFBI gene expressions were associated with decreased OS rather than prolonged survival." (PMID 34888242, 2021). "A recent study identified high levels of PAPP-A in the ascites of ovarian cancer patients and more cleaved than intact IGFBP4, indicating that PAPP-A increased IGF activity and therefore stimulated tumour growth via IGF1-R stimulation." (PMID 30348128, 2018). "Despite large and significant differences between mean IGFBP-4 levels in cases and controls, ROC analysis revealed limited sensitivity at the specificities required for a simple single marker ovarian cancer screening test." (PMID 22264331, 2012). "This study, the first to our knowledge to use RNA-Seq for biomarker discovery, identified IGFBP-4 as overexpressed in ovarian cancer patients." (PMID 22264331, 2012). "Finally, in our analysis, serum IGFBP-4 levels were higher in patients with malignant ovarian tumors than in those with benign tumors and controls." (PMID 41149076, 2025). "In an estrogen-rich environment that may occur as a result of ovarian cancer, IGFBP-4 is thereby over stimulated, and could serve as a marker for this subset of cancers." (PMID 22264331, 2012). "At this time it is unclear how increased levels of IGFBP-4 may relate to initiation or progression of ovarian cancer." (PMID 22264331, 2012). "RT-PCR analyses of ovarian cancer samples validated gene expression profiles of TMEM158, GBE1 and HEG1 from a chromosome 3 transcriptome analysis and IGFBP4, PTRF and C1QTNF1 from a chromosome 17 transcriptome analysis." (PMID 19580657, 2009). "IGFBP4 was significantly elevated in all stages of ovarian cancer patients, even in early stage without elevated CA125." (PMID 36983585, 2023). "Given that CA125 is historically non-informative in ~20% of women with ovarian cancer at the time of their initial diagnosis, we also sought to compare the sensitivity of IGFBP-4 to that of CA125." (PMID 22264331, 2012). "While no previous reports have examined IGFBP-4 serum levels in ovarian cancer patients, IGFBP-4 was one of 52 proteins identified in a proteomic analysis of EOC ascites fluid although serum levels were neither evaluated nor compared with control samples." (PMID 22264331, 2012). "Importantly, we found no previous reports examining serum IGFBP-4 in ovarian cancer in the literature." (PMID 22264331, 2012).